PINX1 (PIN2 (TERF1) interacting telomerase inhibitor 1 )
Gene: Protein-coding gene on chromosome 8 (10,725,399 to 10,839,847, reverse strand). Ensembl gene ENSG00000258724.
Genetic constraint (gnomAD): Loss-of-function variants: 31 observed, 24.7 expected, observed/expected ratio (o/e) 1.25, 90% interval 0.94 to 1.68. The synonymous counts are far from expectation, so gnomAD's model fits this gene poorly and the ratio says little. Missense variants: 639 observed, 483.99 expected, observed/expected ratio (o/e) 1.32, 90% interval 1.24 to 1.41. Synonymous variants: 290 observed, 212.87 expected, observed/expected ratio (o/e) 1.36, 90% interval 1.24 to 1.5.
Diseases named in the same sentence as PINX1 in open-access papers:
PINX1 is named in the same sentence as 60 diseases in open-access papers, as found by Europe PMC text mining. Sharing a sentence is not in itself a finding about the gene and the disease. The quoted sentences say what the papers report.
gastric cancer (7 papers, 2013 to 2017). A primary or metastatic malignant neoplasm involving the stomach. "PinX1 downregulation results in poor prognosis in some cancers, including gastric cancer, prostate cancer, ovarian cancer, and breast cancer." (PMID 28815183, 2017). "Reduced expression of PinX1 has been implicated in various human cancers, such as breast cancer, ovarian cancer, gastric cancer and liver cancer, which suggested a tumor suppressor role of pinX1 in multiple human cancers." (PMID 24936151, 2014). "Previous studies have shown that reduced expression of PinX1 is implicated in various human cancers, including breast cancer, ovarian cancer, gastric cancer, and liver cancer, suggesting that PinX1 may function as a tumour suppressor in multiple human cancers." (PMID 28815183, 2017). "LOH of PinX1 resulted in gastric carcinoma development, which suggested PinX1 might have a potential inhibitory role in cancer metastasis." (PMID 25888829, 2015). "Although the relationship between the PinX1 gene and human tumors has been studied widely, such as in medulloblastoma, hepatocelllular carcinoma, prostate cancer, and gastric cancer, the expression and prognostic value of PinX1 protein has not been investigated in UCB." (PMID 24268029, 2013). "Thus, PinX1 can be regarded as a sign of gastric cancer development." (PMID 27556185, 2016).
breast carcinoma (6 papers, 2011 to 2017). "Our results definitely confirmed that low PinX1 expression is associated with poor prognosis, suggesting that PinX1 may function as a prognostic marker for breast cancer." (PMID 25888829, 2015). "In addition, the potential molecular mechanisms underlying the role of PinX1 in breast cancer are still unclear." (PMID 25888829, 2015). "The role of PinX1 in breast cancer was demonstrated by Zhou which decreased expression of PinX1 was observed in breast cancer cell lines, and knockout of PinX1 in mice could cause different epithelial cancers including breast cancer." (PMID 24672800, 2014). "Overexpression of PinX1 in breast cancer cell lines caused lower growth rate, G0/G1 phase arrest, and S phase inhibition, whereas knockdown of PinX1 in nontumorigenic breast cell line resulted in higher growth rate, decreased G0/G1 phase, and increased S phase rate." (PMID 24672800, 2014). "Although decreased expression of PinX1 was observed in breast cancer cell lines, and knockout of PinX1 in mice could cause breast cancer, the role of PinX1 in growth control of breast cancer cells and its molecular mechanism remains unclear." (PMID 24672800, 2014). "However, the association between PinX1 and NF-κB in breast cancer cells exists indeed." (PMID 25888829, 2015). "In our previous study, we demonstrated that PinX1 suppresses renal cell carcinoma and breast cancer invasion and metastasis in vitro and in vivo." (PMID 27556185, 2016). "We investigated that PinX1 overexpression in breast cancer cells significantly inhibited the formation of metastasis nodules in lung of nude mice." (PMID 25888829, 2015). "PinX1 suppressed breast cancer migration and invasion by inhibiting the expression and activity of MMP-9 via NF-κB-dependent transcription." (PMID 25888829, 2015). "Our data demonstrated that PinX1 inhibited breast cancer cells’ migration and invasion abilities by down-regulating MMP-9 expression and activity in vitro." (PMID 25888829, 2015). "Lastly, we set up the nude mice model by Tail vein assay to exam the functional role of PinX1 in breast cancer metastasis." (PMID 25888829, 2015). "Consistently, the increased ability of migration and invasion induced by PinX1 knockdown was also suppressed by inhibition of NF-κB-p65 expression in breast cancer cells." (PMID 25888829, 2015). "Of the 405 breast cancer analyzed, low and high expression of PinX1 staining were 52.3% (212/405) and 47.7% (193/405), respectively." (PMID 25888829, 2015). "To investigate the mechanisms of PinX1 regulating migration and invasion in breast cancer cells, we performed western blot to detect the MMPs protein levels and gelatin zymography to observe the MMPs activity." (PMID 25888829, 2015). "So we supposed PinX1 suppress migration and invasion of breast cancer cells by regulating MMP-9 expression and activity." (PMID 25888829, 2015). "We then analyzed the correlations between PinX1 expression and characteristics of the breast carcinomas, and found that PinX1 staining was dramatically decreased in histology grade II and III compared with histology grade I (P = 0.001, χ2 test)." (PMID 25888829, 2015). "In the present study, we used a breast cancer TMA containing 405 tumor samples with specific clinical data to investigate the role of PinX1 in human breast cancer." (PMID 25888829, 2015). "Our results confirmed the role of PinX1 as a major tumor suppressor gene in breast cancer cell lines and provided information for further research on the molecular mechanisms of PinX1 in tumorigenesis." (PMID 24672800, 2014). "PinX1 is downregulated in a large subset of human breast cancer tissues and in most breast cancer cell lines examined." (PMID 22021332, 2011). "We show that PinX1 is reduced in most human breast cancer tissues and cells and that reducing PinX1 levels leads to telomerase activation, telomere elongation and chromosome instability." (PMID 22021332, 2011).
breast carcinoma (continued). "Moreover, PinX1 protein expressions are reduced in human breast cancer tissues and most breast carcinoma cell lines." (PMID 27556185, 2016). "Furthermore, we demonstrated that PinX1 suppressed breast cancer migration and invasion by inhibiting the expression and activity of MMP-9 via NF-κB-dependent transcription in vitro and in vivo." (PMID 25888829, 2015). "To further confirm whether PinX1 regulated MMP-9 expression via the NF-κB signaling pathway in human breast cancer cells, we transfected NF-κB-p65 siRNA (Santa Cruz) into PinX1KD-MDA-MB-231 cells and PinX1KD-BT-549 cells." (PMID 25888829, 2015). "This study was designed to evaluate the role of PinX1 in human breast cancer." (PMID 25888829, 2015). "We investigated the involvement of PinX1 in breast cancer cells migration and invasion." (PMID 25888829, 2015). "The univariate Cox regression analyses revealed that PinX1 expression was an independent prognostic marker for breast cancer patients overall survival (hazard ratio, 0.573; 95% CI, 0.371-0.884; P = 0.012) and disease-specific survival (hazard ratio, 0.417; 95% CI, 0.230-0.755; P = 0.004)." (PMID 25888829, 2015). "Moreover, we identified that PinX1 inhibited the migration and invasion of breast cancer by suppressing MMP-9 expression and activity via NF-κB-dependent transcription in vitro." (PMID 25888829, 2015). "In conclusion, loss of PinX1 expression was significantly correlated with breast cancer progression and was an independent negative prognostic factor in breast cancer patients." (PMID 25888829, 2015). "Our study suggested the role of PinX1 as a major tumor suppressor gene in breast cancer cell lines." (PMID 24672800, 2014). "As a major tumor suppressor gene, the role of PinX1 in breast cancer and its molecular mechanism remain unclear." (PMID 24672800, 2014). "In our study, we also found that the overexpression of PinX1 could alter the lncRNA expression profile in MCF-7 breast cancer cells." (PMID 24672800, 2014). "The results showed a lower growth rate in the pcDNA3.1-PinX1 transfected MCF-7 breast cancer cell line than the untransfected and vector transfected control cells and a higher growth rate in the PinX1 knockdown MCF-10A cell line than the untransfected and siRNA NC transfected control cells." (PMID 24672800, 2014). "Lastly, we examined whether PinX1 suppressed breast cancer metastasis in vivo." (PMID 25888829, 2015). "Finally, our mice model confirmed that PinX1 suppressed breast cancer metastasis in vivo." (PMID 25888829, 2015). "Moreover, we examined whether PinX1 expression was an independent prognostic factor for breast cancer." (PMID 25888829, 2015). "However, the role of PinX1 in growth control of breast cancer cells and its molecular mechanism remains unclear." (PMID 24672800, 2014). "Furthermore, PinX1 is reduced in a large subset of human breast cancer tissues and cells." (PMID 22021332, 2011). "To evaluate the function of PinX1 in breast cancer, we used a tissue microarray (TMA) of 405 human breast cancer patients and immunohistochemistry to analyze the correlation between PinX1 expression and clinicopathologic variables and patient survival." (PMID 25888829, 2015). "Therefore PinX1 may be an attractive therapeutic target for the treatment of breast cancer." (PMID 25888829, 2015). "To evaluate the function of PinX1 in breast cancer, we used a tissue microarray (TMA) of human breast cancer patients and immunohistochemistry to analyze the correlation between PinX1 expression and clinicopathologic variables and patient survival." (PMID 25888829, 2015). "Recent years, our research team validated that low PinX1 expression was an independent negative prognostic factor for clear cell renal cell carcinoma (ccRCC), breast cancer (BC) and gliomas patients." (PMID 27556185, 2016). "Cox regression analysis revealed that low PinX1 expression was an independent negative prognostic indicator for breast cancer patients." (PMID 25888829, 2015).
breast carcinoma (continued). "Our data revealed that low PinX1 expression was an independent negative prognostic factor for breast cancer patients." (PMID 25888829, 2015). "We found a lower growth rate, G0/G1 phase arrest, and S phase inhibition in the PinX1 overexpressed breast cancer cells, while a higher growth rate, decreased G0/G1 phase, and increased S phase rate in the PinX1 knocked-down nontumorigenic breast cell." (PMID 24672800, 2014). "In this study, overexpression of PinX1 was generated in 3 breast cancer cell lines, and knockdown of PinX1 was performed in a nontumorigenic breast cell line." (PMID 24672800, 2014). "The qRT-PCR and western blotting results indicated that pcDNA3.1-PinX1 transfected breast cancer cell lines MCF-7, MDA-MB-231 and SK-BR-3 showed a higher PinX1 expression level than their counterpart untransfected cells and empty vector transfected control cells." (PMID 24672800, 2014). "However, the expression and function of PinX1 in breast cancer and its correlation with the clinicopathological features of breast cancer patients have never been investigated." (PMID 25888829, 2015). "However, the PinX1 expression status and its correlation with the clinicopathological features in breast cancer have never been investigated." (PMID 25888829, 2015). "However, overexpression or knockdown of PinX1 had no detectable effect on the proliferation of breast cancer cells under normal culture conditions (data not shown)." (PMID 25888829, 2015). "Therefore, in this study, we generated MCF-7, MDA-MB-231, and SK-BR-3 breast cancer cells stably overexpressing PinX1 and MCF-10A nontumorigenic breast cell knocking down PinX1 and assessed the role of PinX1 in growth control of the cells by MTT assay, focus formation, and flow cytometry." (PMID 24672800, 2014).
ovarian carcinoma (6 papers, 2014 to 2024). A malignant neoplasm originating from the surface ovarian epithelium. "Our finding provided epidemiologic evidence that PINX1 genetic variants could affect ovarian cancer outcome through telomere maintenance pathway." (PMID 28233473, 2017). "To further assess the impact of PINX1 deficiency on the efficacy of PARP inhibitors in vivo, we established a xenograft model in NSG mice using ovarian carcinoma-derived cell line OC316 with or without PINX1 knock-down." (PMID 39174499, 2024).
prostate carcinoma (6 papers, 2012 to 2020). A carcinoma that arises from epithelial cells of the prostate gland. "For example, studies on 159 cases of hereditary prostate cancer identified 39 polymorphisms during PinX1 sequencing; studies on gastrointestinal cancer also found a missense mutation (AGC/TGC) out of 254 codons in 1 case of colon cancer and 1 case of esophageal cancer." (PMID 22316341, 2012). "However, some studies on prostate cancer, gastrointestinal cancer and medulloblastoma indicate that gene polymorphism rather than PinX1 expression is the key factor in inhibiting telomerase and PinX1 as a microtubule binding protein plays an important role in stabilizing chromosome." (PMID 22316341, 2012). "However, the PinX1 expression status and its correlation with the clinicopathological features in prostate cancer (PCa) have not been investigated." (PMID 24936151, 2014).
lung carcinoma (5 papers, 2016 to 2022). "Moreover, we use pinX1 siRNA to investigate the underlying mechanisms, and a similar experiment in vivo based on pinX1 transgenic mice will provide more clues for the study of the mechanism of hesperidin against lung cancer." (PMID 35847001, 2022). "It is also indeed important to detect the pinX1 expression profile in other lung cancer cell lines and to verify the broad applicability of the anti-lung cancer effect of hesperidin." (PMID 35847001, 2022). "In order to investigate the role of pinX1 in lung cancer, the pinX1 expression was knocked down by its specific siRNA in vitro." (PMID 35847001, 2022). "The PinX1 protein was highly expressed in 46 of the 86 (53.49%) lung cancer tissues, while the low expression of pinX1 was observed in 77 of the 86 (89.53%) adjacent samples." (PMID 35847001, 2022). "In order to explore the role of pinX1 in exact lung cancer, the role of pinX1 was investigated using a shared database." (PMID 35847001, 2022). "In this study, we found that the pinX1 expression level is closely related to overall survival and plays an important role in regulating lung cancer cell proliferation, migration, invasion, and senescence." (PMID 35847001, 2022). "In HPA, we found that the expression of pinX1 was poor in normal lung tissues, whereas the staining intensity was moderate or strong in lung cancer." (PMID 35847001, 2022). "LncRNA CCAT2 can promote the proliferation of lung cancer cells by affecting Wnt signaling pathway, lncRNA PinX1 can block the growth of lung cancer cells in G0/G1 phase, thus inhibiting the proliferation of lung cancer and acting as anti-tumor effect." (PMID 33976738, 2021). "Since PinX1 is an inner telomerase inhibitor, we first detected the effects of PinX1 on telomerase activity in lung cancer cells." (PMID 28815183, 2017). "In this study, we found that hesperidin inhibits lung cancer in vitro and in vivo via pinX1." (PMID 35847001, 2022). "Interestingly, the pinX1 protein expression in lung cancer patients is positively related to overall survival time, which is in accordance with a study on thyroid cancer." (PMID 35847001, 2022). "Differential expression of pinX1 in lung cancer and adjacent tissues." (PMID 35847001, 2022). "According to our mutation data, PinX1 mutations in gastric, colorectal, prostate, breast, and lung carcinomas may not actually contribute to development of these carcinomas due to their low incidence of mutational events seen in the database." (PMID 28978030, 2017).
lymph node metastasis (5 papers, 2014 to 2018). "Nine, 11, 12, 11, 10, and 5 studies reported associations between PINX1 expression and sex, depth of invasion, lymph node metastasis, tumor differentiation, tumor-node-metastasis (TNM) stage, and distant metastasis, respectively." (PMID 30079348, 2018). "With respect to the clinicopathological characteristics, we showed that low PINX1 expression was associated with lymph node metastasis and advanced TNM stage." (PMID 30079348, 2018). "The results of the pooled analysis showed that low PINX1 expression was associated with lymph node metastasis (OR: 2.23, 95.0% CI: 1.35–3.70; P = 0.002) and advanced TNM stage (OR: 2.43, 95.0% CI: 1.29–4.57; P = 0.006)." (PMID 30079348, 2018). "We found that low PinX1 expression was associated with lymph node metastasis (P = 0.002) and histology grade (P = 0.001) in patients, as well as with poorer overall and disease-specific survival (P = 0.010 and P = 0.003, respectively)." (PMID 25888829, 2015). "Our data showed that low PinX1 expression was associated with lymph node metastasis and histology grade in patients, as well as with poorer overall and disease-specific survival." (PMID 25888829, 2015). "Low PinX1 expression was significantly correlated with depth of invasion, lymph node metastasis and advanced TNM stage in patients, as well as with worse overall and disease-specific survival." (PMID 26033551, 2015). "We also found that PinX1 expression is significantly correlated with lymph node metastasis (P = 0.002, χ2 test)." (PMID 25888829, 2015). "Reduced expression of PinX1 in patients was correlated with advanced clinical stage (χ2 = 10.230, p = 0.017), high Gleason score (χ2 = 4.019, p = 0.045), positive regional lymph node metastasis (χ2 = 10.852, p = 0.004) and distant metastasis (χ2 = 7.965, p = 0.005)." (PMID 24936151, 2014).
non-small cell lung carcinoma (5 papers, 2017 to 2024). A group of at least three distinct histological types of lung cancer, including non-small cell squamous cell carcinoma, adenocarcinoma, and large cell carcinoma. "We aimed to investigate the effects of PinX1 on non-small cell lung cancer(NSCLC) radiosensitivity and radiotherapy-associated tumor immune microenvironment and its mechanisms." (PMID 38431575, 2024). "The results of the subgroup analysis showed that low PINX1 expression was associated with significantly poorer OS in colorectal cancer, non-small cell lung cancer, sample size (> 150), and test method (IHC + TMA)." (PMID 30079348, 2018). "In a subgroup analysis of tumor type, low PINX1 expression was associated with significantly poorer OS for colorectal cancer (HR: 2.28, 95.0% CI: 1.46–3.56; P < 0.001) and non-small cell lung cancer (HR: 1.48, 95.0% CI: 1.06–2.08; P = 0.023)." (PMID 30079348, 2018). "For instance, PinX1 expression has recently been proposed as a prognostic factor for human non-small cell lung cancer." (PMID 31210926, 2019). "However, the clinical and biological significance of PinX1 in human non-small cell lung cancer (NSCLC) is unclear." (PMID 28372542, 2017). "Therefore, PINX1 expression is a potential biomarker of prognostic significance for OS and DFS/RFS in colorectal cancer and non-small cell lung cancer." (PMID 30079348, 2018). "PinX1 expression status and its correlation with clinicopathological features in non-small-cell lung cancer (NSCLC) have not been investigated." (PMID 28815183, 2017).